LCK (LCK proto-oncogene, Src family tyrosine kinase)
Diseases named in the same sentence as LCK in open-access papers (continued):
Sharing a sentence is not in itself a finding about the gene and the disease.
tumor (continued). "To determine differences in LCK expression in multiple tumor tissues, we applied established computational approaches (UALCAN, TCPA) to analyze the LCK mRNA and protein levels from The Cancer Genome Atlas (TCGA)." (PMID 32237064, 2020). "Although CD8-LCK is essential for fine-tuning cytotoxic T-cell responses to weak antigens in a kinase-dependent manner, CD8-bound LCK appears largely dispensable for the in vivo development of cytotoxic T cells and anti-viral/anti-tumor responses." (PMID 41601693, 2026). "Intriguingly, DSF treatment impaired LCK activation in both tumor-infiltrating CD4+ and CD8+ T cells (data not shown)." (PMID 40759573, 2025). "Thus, we developed CD33 CAR constructs overexpressing LCK, ZAP70, C-JUN, C-Fos, and IFN-γ, and that overexpressing IL-15, a cytokine known to potentiate CAR T therapeutic activity in various tumor models, as a control." (PMID 39039086, 2024). "Considering the paired sample differential analysis, expression correlation analysis, immunological and tumour microenvironment correlation analysis, as well as the line chart results, CEMACAM3, LCK, PARP1, PDGFB, PLK1, SEMA7A and SPHK1, were considered as prognostic genes of higher value." (PMID 39656479, 2024). "This resulted in better control of tumor growth in NSG mice engrafted with the neuroblastoma tumor cell line CHLA-255 as compared to CD28 co-stimulated CAR-T cells without co-expressing LCK." (PMID 35053463, 2022). "The expression levels of CCL5, CD3E, and LCK were lower in tumor tissues samples than those in adjacent non-tumor tissue samples, which is consistent with the results of transcriptomics." (PMID 34218795, 2021). "While there was no clear correlation between LCK expression and increasing tumor stages, the level of LCK increased with higher tumor grading (G1 vs. G2: p = 4.64E-03; G2 vs. G3: p = 1.00E-04; G3 vs. G4: p = 0.055)." (PMID 34116687, 2021). "However, both AURKA and AURKB expression were significantly inversely correlated with markers for T-cell infiltration of the tumor: CD3E, CD4, CD8A, LCK, PDCD1 and IFNG." (PMID 33123754, 2021). "In contrast, several proteins, including PREX1, LCK, PD-L1, transglutaminase, and cleaved caspase 7, were elevated in the CHIM subgroup, which might be predictors of “hot tumor”." (PMID 34177954, 2021). "Finally, we investigated the connection between tumor grades and hub genes, in which LCK, CD2, CD3D, IFNG, CD8A, and CCL5 showed significant correlation with different tumor grades (p < 0.05), with grade increase corresponding to increased gene expression." (PMID 32081834, 2020). "The data from the ‘gene’ module of TIMER showed that LCK mRNA expression had a significant negative correlation with tumor purity in GBM, but not in DLBCL (GBM, r = −0.318, P = 2.49E‐11; DLBCL, r = −0.08, P = 6.15E‐1)." (PMID 32237064, 2020). "Although we did not observe any differences in the CIBERSORT 22 immune subsets between responders and non-responders, of the 6 Rody metagenes that we applied (MHC-I, MHC-II, HCK, LCK, IFN, and STAT1), C+K+ tumours expressed higher levels of the MHC-II metagene (p = 0.0696) than other tumours." (PMID 30478407, 2018). "The expression of the TFs from this immune response module is correlated with an increase in the number of Tumour-infiltrating lymphocytes in the TCGA-BRCA dataset and the expression of activated Caspase-7, LCK and SYK proteins indicating an active immune response." (PMID 28588211, 2017). "Consistent with the DASL data, the CTLA4 and LCK genes in TCGA RNAseq data demonstrated up-regulated expression in tumor compared to matched normal in the young cohort but not in the older cohort." (PMID 28027300, 2016). "LCK was more highly expressed in oestrogen receptor (ER)-negative, compared with ER-positive tumours." (PMID 20717116, 2010).
tumor (continued). "CAR T cells overexpressing LCK effectively controlled tumor progression at an early stage, but the effect was not as long-lasting as that of ZAP70 or C-JUN, whereas overexpression of C-JUN showed the greatest effect in improving tumor control and prolonging mouse survival." (PMID 39039086, 2024). "Furthermore, lymphatic invasion—a clinical tumor characteristic—of immune genes, including CD27, CD48, and CD28, as well as infiltration of CD8+ T cells exhibited a positive and substantial connection with LCK expression (in terms of immune cells)." (PMID 37773310, 2023). "Given the role of many SFKs in immune signaling pathways, increased phosphorylation of SFKs, such as LCK, LYN, FYN, and FGR could be associated with immune cell activation, rather than tumor cell signaling." (PMID 36077757, 2022). "Therefore, since LCK plays a role in cancer cell signaling as well as in T-cell function, it will be necessary to define therapeutic strategies to selectively target LCK in tumor cells without impairing the responses of tumor infiltration lymphocytes." (PMID 36341345, 2022). "In addition, the myeloid cell line 32D and several non-lymphoid human tumor cell lines also show LCK expression." (PMID 29062038, 2017). "In addition, higher expression of LCK has been confirmed in this work that it also upregulated the expression levels of CXCL9, CXCL10, and CXCL 11, which were reported to initiate a chemokine network to contribute to the generation of a “hot” (or T-cell–inflamed) tumor microenvironment." (PMID 36561315, 2022). "We also detected somewhat puzzling hypermethylation and silencing of genes that would be predicted to be oncogenes, rather than tumor suppressors, such as SF3B1, LCK, FOXP1, and FYN." (PMID 39189258, 2024). "We also detected somewhat puzzling hypermethylation and silencing of genes that would be predicted to be oncogenes, rather than tumor suppressors, such as SF3B1, LCK, FOXP1, FYN50,51." (PMID 38464090, 2024). "Because of the absence of the major substrate of CD45, LCK, it is plausible that in ALK+ ALCL the CD45 phosphatase activity affects the JAK/STAT pathway therefore playing a role as a tumor suppressor." (PMID 36698412, 2022). "Compared with normal control tissues, the expression level of CD3D and CD2 in tumor tissues were not significantly different, while the expression levels of CD3E, CD3G, CCL5, CXCR6 and LCK in tumor tissues were lower than those in normal tissues (P < 0.05)." (PMID 34218795, 2021). "In addition, tumor heterogeneity was observed, given that only THYM patient samples showed a significantly negative correlation between LCK expression and macrophage abundance." (PMID 36430477, 2022).
cancer (73 papers, 2003 to 2026). A tumor composed of atypical neoplastic, often pleomorphic cells that invade other tissues. "KEGG and GO enrichment analyses showed that LCK was significantly associated with PD-L1 expression, T cell receptor signaling pathway, and PD-1 checkpoint pathway in cancers." (PMID 36430477, 2022). "In line with that, GPR171 expression is well associated with T-cell signature genes CD3e and LCK across multiple cancer types in The Cancer Genome Atlas (TCGA) database." (PMID 34615877, 2021). "Integrative gene expression analysis identified the Lymphocyte cell-specific protein-tyrosine kinase (LCK) as a druggable target gene associated with cancer cell invasion and metastasis." (PMID 34116687, 2021). "LCK is a druggable target gene associated with cancer cell invasion and metastasis." (PMID 37891201, 2023). "In contrast, the inhibited targeted drugs of LCK was reported that could cause the loss of T-cell immune response and result in immunosuppression for patients cancer." (PMID 33748188, 2021). "All together, these data suggest that artificial regulation of LCK or screening for LCK variants could inform immune-based therapeutic strategies for cancer." (PMID 34012443, 2021). "Consequently, genetic variations and mutations that alter the function of LCK have profound implications for the development of cancer and immune-based therapies." (PMID 34012443, 2021). "Due to LCK’s essential function in T-cell responses, various strategies have been devised to redirect LCK activity, to enhance the efficacy of chimeric antigen receptors (CARs) and augment T-cell responses in the context of cancer immunotherapy." (PMID 40565031, 2025). "CDKN2A was significantly upregulated, while LCK, key gene in the maintenance of the undifferentiated state, was significantly downregulated in MSCs vs. cancer cells and iPSC lines." (PMID 39621192, 2025). "LCK activity can improve the efficacy of chimeric antigen receptors (CARs) and to potentiate T-cell responses in cancer immunotherapy." (PMID 38903179, 2024). "For instance, increased expression of LCK, ITGA5, CGH1 and TNFRSF9 was associated with increased drug sensitivity of cancer cells to ribavirin, nelarabine, zalcitabine, bleomycin, asparaginase, dexrazoxane, palbociclib, etc." (PMID 38903179, 2024). "Concurrent inhibition of LCK enhanced the efficacy of PARPi in HR proficient cancer models in preclinical settings." (PMID 37370140, 2023). "Multiple databases were used to explore the expression, alteration, prognostic value, association with immune infiltration, and potential functional pathways of LCK in pan-cancers." (PMID 36430477, 2022). "Most of the down-regulated hub proteins (ESR1, MCL1, LCK, TBP, and PCNA) play roles in the proliferation or survival of cancer cells, and CHEK1 is associated with the cell cycle checkpoint in cancer cells." (PMID 35563525, 2022). "We demonstrate that USP11 plays an oncogenic role in lymphoid malignancy and controls LCK activity in association with USP7 via LCK deubiquitination." (PMID 36490346, 2022). "Next, we focused mainly on the relationship between LCK and immune checkpoints in different cancer types." (PMID 36430477, 2022). "As an important tyrosine kinase of the Src family, several studies on LCK have been conducted in solid tumors and have suggested its cancer-promoting functions." (PMID 36430477, 2022). "In this study, pan-cancer analysis based on a variety of databases was used to explore the role of LCK in human tumors, including their occurrence, development, progression, and potential signaling pathways." (PMID 36430477, 2022). "One such tyrosine kinase is LCK which has been reported to be an important participant in the pharmacological control of vast array of diseases like cancer and immune-mediated autoimmune and inflammatory conditions." (PMID 36144198, 2022). "The results from the PrognoScan database showed more distinct roles for LCK in the prognosis of different cancers." (PMID 36430477, 2022).
cancer (continued). "In multiple dataset validations, the expression levels of CCL5, CXCR6, CD3E, and LCK were decreased in cancer tissues." (PMID 34218795, 2021). "Pan-cancer analysis also revealed a positive correlation between LCK/CD3E and TMB in several types of cancers, despite the coefficients being small." (PMID 35004669, 2021). "In multiple dataset validations, CCL5, CXCR6, CD3E and LCK were identified to be down-regulated in cancer tissues." (PMID 34218795, 2021). "Recent studies showed that the improved LCK activity was contributed to improve the efficacy of chimeric antigen receptors (CARs) immunotherapy in cancers." (PMID 33748188, 2021). "Inhibition of LCK using a clinically approved drug, i.e. dasatinib, induced cancer cell differentiation and impaired cell motility by enhancing the formation of adherens junctions." (PMID 34116687, 2021). "Early studies demonstrated that LCK was widely expressed in immune cells and was a potential biomarker of malignant tumors." (PMID 35004669, 2021). "Given this anticipated initial chemosensitization step, we pursued pretreatment with LCK inhibitors followed by co-treatment with cisplatin and found that this technique was effective in decreasing cancer cell populations and increasing apoptosis in vitro." (PMID 33888137, 2021). "Immunohistochemistry results demonstrated that CCL5, CD3E and LCK were expressed at low levels in HCC cancer tissues." (PMID 34218795, 2021). "The immunohistochemistry results demonstrated that the staining intensity of CCL5, CD3E and LCK in HCC cancer tissues ended to be decreased compared with those in normal tissues." (PMID 34218795, 2021). "Of all of the other family members (FYN, YES, BLK, YRK, FGR, HCK, LCK, and LYN) cSrc is the most often associated with cancer progression." (PMID 33841333, 2021). "Lastly, we provide a rationale for continued investigation of the complex interplay between anti-cancer immune response and the activity of LCK and TEC kinases." (PMID 33213062, 2020). "There are 36 protein kinases in the Cancer Gene Census; seven of them (EGFR, ERBB2, BRAF, FLT3, PRKACA, LCK, and FGFR2) had enriched PTM/mutation domains in our study." (PMID 29695735, 2018). "LCK and HLA-A displayed similarly positive correlations in both cancers with all markers except NOS2 (iNOS), which was observed only in the two PDAC data sets." (PMID 27762323, 2016). "In this study, we identified lymphocyte-specific protein tyrosine kinase (LCK), which correlates with cancer malignancy, as a binding partner of FOXP3." (PMID 24155921, 2013). "This indicates that LCK inhibition attenuates HR repair efficiency in cancer cells." (PMID 37370140, 2023). "Interestingly, metastatic BC showed lower neutrophil infiltration and significantly lower LCK expression, which further confirms the correlation between LCK, neutrophil infiltration, and cancer metastasis and prognosis." (PMID 37686072, 2023). "Recent studies suggest that LCK may have tumorigenic and cancer-promoting functions in multiple tumors." (PMID 36430477, 2022). "Given the prominent therapeutic functions and recently accumulated evidence on tumors of LCK, an integrative and comprehensive pan-cancer analysis may help us further understand its functions in the development and progression of tumors." (PMID 36430477, 2022). "In conclusion, LCK may play a critical role in immune cell signal transduction and serve as a potential prognostic and therapeutic biomarker in several cancers." (PMID 36430477, 2022). "The biological function of LCK differs depending on the cancer type." (PMID 36430477, 2022).
cancer (continued). "Of note, the TIL-B and TIL-T cells, measured by the CD20 and LCK protein levels, showed different prognostic trends across various subgroups, which indicated that the TILs play a complex role under the heterogeneous context of cancer subtypes." (PMID 35069521, 2021). "With our initial results and proposed mechanism of action of chemosensitization, we hypothesized that treating cancer cells first with an LCK inhibitor, followed by co-treatment with an LCK inhibitor and cisplatin, would enhance the chemosensitization effect." (PMID 33888137, 2021). "Interestingly, five genes (CD247, CD3E, ZAP70, LCK, PTPN6) were associated with the hsa05235 pathway (PD-L1 expression and PD-1 checkpoint pathway in cancer)." (PMID 34880861, 2021). "However, LCK has also been found expressed in several solid tumors including brain, breast, prostate, and colorectal cancer." (PMID 34830895, 2021). "In addition, LCK has been shown to be overexpressed in many cancer types and LCK inhibitors have been clinically used to treat a number of solid cancers." (PMID 33345267, 2021). "LCK is one of the key molecules regulating T-cell responses in cancer immunotherapy." (PMID 33344244, 2020). "LCK’s association with positive therapeutic outcomes in solid human cancers is likely due to immune response, rather than intrinsic cancer cell LCK abnormalities." (PMID 33233470, 2020). "Therefore, LCK has emerged as a novel druggable target molecule for the treatment of cancer and neuronal diseases." (PMID 32237064, 2020). "As a new target of rhein, LCK might play an important role in the treatment of cancer or inflammation." (PMID 30189851, 2018). "Apart from cells of hematopoietic origin, LCK is also aberrantly expressed in a number of other cancer types, including breast cancer, colon cancer and small cell lung carcinoma suggesting that it has general cancer promoting activities." (PMID 29062038, 2017). "LCK is a non receptor protein-tyrosine kinase of the Src oncogene family mostly expressed in T cells, where it plays an essential role in activation and development, and in some B cells and other cancer tissues." (PMID 21042412, 2010). "Therefore, the application of LCK inhibitors could be an important strategy for the treatment of certain cancers." (PMID 36341345, 2022). "This suggests that LCK may become a new target gene for cancer therapy." (PMID 35480305, 2022). "Nonetheless, the detailed role of LCK in specific types of cancers remains unclear." (PMID 36430477, 2022). "Since we and others identified LCK as an important regulator of cancer cell motility, it would be interesting to investigate, if patient stratification based on intratumoral LCK expression could identify additional patient populations that would benefit from single agent or combination therapy." (PMID 34116687, 2021). "Lymphocyte-specific protein tyrosine kinase (LCK) phosphorylates Tyrosine-342 of FOXP3 and upregulates its expression resulting in decreased Matrix metalloproteinase 9 (MMP9), S-phase kinase-associated protein 2 (SKP2), and Vascular endothelial growth factor A (VEGF-A) levels in cancer cells." (PMID 33614551, 2021). "Next, we analyzed the relationships of LCK with IFNG, CCL5, and CXCR3, using TCGA bulk RNA-sequencing data, and we found significant associations in the expression levels of LCK with IFNG (total rho=0.73), CCL5 (total rho=0.80), and CXCR3 (total rho=0.84) in most cancer types." (PMID 35069521, 2021). "The expression perturbation results of hub PPMEs between normal and cancer samples revealed that hub PPMEs were significantly different between normal and cancer samples, except EGFR, LCK, and YES1, and they had higher expression levels in cancer samples." (PMID 39940833, 2025). "The general function of LCK and PTPRC is T and B cell signalling but regarding cancer, they participate in cell proliferation and tumourigenesis, respectively." (PMID 37277696, 2023).